UNC5B (unc-5 netrin receptor B)
Diseases named in the same sentence as UNC5B in open-access papers (continued):
Sharing a sentence is not in itself a finding about the gene and the disease.
breast carcinoma (continued). "In summary, our study provides a comprehensive understanding of the role of UNC5B in breast tumorigenesis and better defines the value of UNC5B in breast cancer management." (PMID 32902412, 2020). "We subsequently analyzed UNC5B expression in three major histological subtypes of breast cancer, including invasive ductal breast carcinoma, lobular breast carcinoma, and mixed lobular and ductal breast carcinoma." (PMID 32902412, 2020). "High UNC5B expression and poor OS are correlated, further suggesting UNC5B as a potential prognostic biomarker in breast cancer." (PMID 32902412, 2020). "Consistently, UNC5B expression was higher in tumors than in adjacent normal tissues among these three breast cancer subtypes." (PMID 32902412, 2020). "Compared with normal breast tissues, UNC5B mRNA expression was significantly upregulated in breast cancer tissues in 14 datasets (p < 0.05)." (PMID 32902412, 2020). "The phosphorylation of PI3K and Akt were significantly blunted in UNC5B-knockdown breast cancer cells compared with breast cancer cells treated with NC-shRNA, suggesting the essential role of UNC5B in PI3K/Akt pathway activation." (PMID 32902412, 2020). "Here, we discovered that UNC5B was altered in 24 of 180 sequenced breast cancer patient samples (13%) and that the major type of UNC5B alteration was amplification." (PMID 32902412, 2020). "The top 50 genes positively and negatively correlated with UNC5B in breast cancer are shown in heat maps." (PMID 32902412, 2020). "We then evaluated correlations between UNC5B expression and clinicopathological features in breast cancer patients." (PMID 32902412, 2020). "The results showed that increased UNC5B expression was significantly correlated with poor OS in breast cancer patients." (PMID 32902412, 2020). "In this study, we showed that UNC5B was frequently overexpressed in breast cancer." (PMID 32902412, 2020). "In addition, our results showed that UNC5B knockdown significantly inhibited the proliferation and metastasis of breast cancer cells, underscoring the essential role of UNC5B in breast cancer development." (PMID 32902412, 2020). "Similarly, we verified that UNC5B expression was upregulated in breast cancer cell lines and breast cancer tissues using Western blot and IHC, respectively." (PMID 32902412, 2020). "We then investigated the prognostic value of UNC5B in breast cancer." (PMID 32902412, 2020). "High UNC5B expression was correlated with poor prognosis in breast cancer patients." (PMID 32902412, 2020). "In addition, we analyzed UNC5B expression in breast cancer tissues and normal breast tissues using immunohistochemistry (IHC)." (PMID 32902412, 2020). "UNC5B was expressed at a higher level in breast cancer tissues than in normal tissues." (PMID 32902412, 2020). "Further work is required to validate the spectrum of UNC5B genomic alterations, and in vivo experimental investigations are needed to validate the essential role of UNC5B in breast cancer, which could contribute to the development of precision medicine." (PMID 32902412, 2020). "High UNC5B expression was correlated with poor overall survival in breast cancer patients." (PMID 32902412, 2020). "We further investigated the effect of UNC5B on breast cancer metastasis." (PMID 32902412, 2020). "Along this line, UNC5B overexpression in breast cancer as observed in our study could be a selective advantage for tumorigenesis, as increased expression of netrin-1 was seen in the majority of breast tumors with metastatic tendency." (PMID 32902412, 2020). "Protein level validation in a breast cancer TMA confirmed that high UNC5B expression could serve as a biomarker for poor prognosis in breast cancer." (PMID 32902412, 2020). "To demonstrate whether UNC5B regulates the PI3K/Akt signaling pathway in breast cancer, we analyzed PI3K/Akt pathway activation using Western blot analysis." (PMID 32902412, 2020). "Thus, UNC5B is a promising target for individualized breast cancer management." (PMID 32902412, 2020).
breast carcinoma (continued). "In addition, the molecular functions of UNC5B in breast cancer were evaluated in vitro." (PMID 32902412, 2020). "In our study, UNC5B co-expressed genes were significantly enriched in the PI3K/Akt signaling pathway and UNC5B depletion in breast cancer cells markedly inhibited the PI3K/Akt pathway." (PMID 32902412, 2020). "By using a breast cancer tissue microarray (TMA), we further evaluated the prognostic value of UNC5B at the protein level." (PMID 32902412, 2020). "Nevertheless, the expression level of UNC5B and its clinical relevance in breast cancer have not been fully elucidated." (PMID 32902412, 2020). "We further evaluated UNC5B protein expression in diverse breast cancer cell lines and MCF 10A cells, a nontumorigenic breast epithelial cell line, by performing Western blot." (PMID 32902412, 2020). "Moreover, UNC5B knockdown mitigated the aggressiveness of breast cancer cells and compromised PI3K/Akt pathway activation, suggesting UNC5B as a new therapeutic target for breast cancer." (PMID 32902412, 2020). "One limitation of our study was that the UNC5B genomic alteration data in breast cancer were obtained from online databases and were not validated in our datasets." (PMID 32902412, 2020). "Western blot analysis confirmed a marked decrease in UNC5B expression in UNC5B-shRNA treated breast cancer cells compared to the negative control (NC)-shRNA treated cells." (PMID 32902412, 2020). "Further subgroup analyses confirmed that UNC5B expression was upregulated in breast cancer tissues consistently, regardless of histological subtypes and other clinicopathological features, including gender, race, menopause status, molecular subtype, and cancer stage." (PMID 32902412, 2020). "Consequently, targeting UNC5B may enhance the clinical application of PI3K inhibitors and improve the prognosis of breast cancer patients." (PMID 32902412, 2020). "However, the exact expression pattern and mechanism of UNC5B in breast cancer have not been well elucidated." (PMID 32902412, 2020).
colorectal cancer (8 papers, 2015 to 2023). A primary or metastatic malignant neoplasm that affects the colon or rectum. "UNC5B has been found to be expressed in colorectal cancer, and its expression level is associated with prognosis and recurrence." (PMID 35035481, 2022). "The mRNA expression of NEO1 was increased (p < 0.05) in HT-29 cells and gene expression levels of UNC5B remained unchanged in both colorectal cancer cell lines." (PMID 36831381, 2023). "RNA-seq TCGA dataset also showed a significant decrease of UNC5B exon 8 inclusion in colorectal cancers compared to the normal tissues." (PMID 34381052, 2021). "Higher expression of UNC5B can inhibit cellular proliferation in some cancer cell lines, and this protein is inactive and downregulated in colorectal cancer." (PMID 30696739, 2019). "Interestingly, NTN4 shares the laminin domain with netrin-1 (NTN1), and there is evidence that NTN4 could exert its angiogenic roles via indirect interaction with the NTN1 putative receptors Unc-5 netrin receptor B (UNC5B) and Deleted in colorectal carcinoma (DCC)." (PMID 33923095, 2021).
thyroid cancer (7 papers, 2019 to 2024). "The results showed that eight key genes (NUAK2, TNFRSF10B, TNFRSF10C, TNFRSF12A, UNC5B, and PMAIP1) exhibited good diagnostic performance in differentiating between thyroid cancer patients and controls." (PMID 39104814, 2024). "The netrin–UNC5B signaling pathway, lipids and atherosclerosis, thyroid cancer, and modulation of PTEN gene transcription were the top five functional descriptions discovered using data mining on citrinin targets." (PMID 37109409, 2023). "The role of UNC5B in other tumors has been confirmed, but its role in thyroid cancer has rarely been studied." (PMID 32596158, 2020). "UNC5B expression is dysregulated in many cancers, including colorectal, bladder, and thyroid cancer and UNC5B knockdown suppresses the proliferation, migration, and invasion of thyroid cancer cells." (PMID 32902412, 2020). "UNC5B plays an important role in the development of multiple cancers, including colorectal, bladder, and thyroid cancer." (PMID 32902412, 2020). "Meanwhile, UNC5B expression was significantly higher in cholangiocarcinoma, kidney renal clear cell carcinoma, and thyroid carcinoma compared with adjacent normal tissues (p < 0.001)." (PMID 32902412, 2020). "When data mining was performed on citrinin targets, the top five functional descriptions were a cell’s response to an organic cyclic compound, the netrin–UNC5B signaling pathway, lipids and atherosclerosis, thyroid cancer, and controlling the transcription of the PTEN gene." (PMID 37109409, 2023). "However, their findings came to opposite conclusion that UNC5B knockdown decreased thyroid cancer progression." (PMID 32760219, 2020). "TNFRSF10B, TNFRSF10C, TNFRSF12A, UNC5B, PMAIP1, and IL18 had increased expression in thyroid cancer tissues, while NUAK2 was decreased." (PMID 39104814, 2024).
atherosclerosis (5 papers, 2021 to 2023). A disease characterized by the build-up of fatty material and calcium deposition in the arterial wall resulting in partial or complete occlusion of the arterial lumen. "Elevated levels of UNC5B are associated with chronic inflammation such as atherosclerosis obesity, oxygen-induced retinopathy, and retinal vessel sprout." (PMID 35008701, 2021). "Altogether this study demonstrates for the first time that netrin-1 secreted by plaque macrophages actively promotes the progression of atherosclerosis in an Unc5b-dependent manner." (PMID 35008701, 2021). "The downregulation of ICAM-1, IL-6, and MCP-1 that can also be induced by the UNC5B blockade was also observed in atherosclerosis patients." (PMID 35008701, 2021). "Moreover, we found that Unc5b was fucosylated by Fut8, which mainly mediated macrophage retention during the progression of atherosclerosis." (PMID 36670464, 2023). "Importantly, we also found that hypofucosylation of Unc5b regulated by Fut8 enhanced macrophage emigration from intimal lesions and further prevented atherosclerosis through the p-CDC42/p-PAK signaling pathway." (PMID 36670464, 2023). "Therefore, further research in mice with macrophage-specific Unc5b overexpression or knockout will be conducted and will provide more specific evidence to clarify the role of Unc5b in atherosclerosis." (PMID 36670464, 2023). "Then we found that the colocalization of Unc5b, Fut8 and CD68 in the aortic sinus were strongly promoted during the development of atherosclerosis as indicated in the Development group." (PMID 36670464, 2023). "Moreover, Unc5b regulated the migration process through activation of the p-PAK/p-CDC42 signaling pathway, which highlights the potential of this receptor as a therapeutic target for atherosclerosis." (PMID 36670464, 2023).
glioma (4 papers, 2013 to 2024). A benign or malignant brain and spinal cord tumor that arises from glial cells (astrocytes, oligodendrocytes, ependymal cells). "We therefore concluded that the signaling pathways of the dependence receptors might be functional in both glioma cell lines and UNC5B can be potentially responsible for the loss of their survival upon silencing of APPL2 expression." (PMID 22989406, 2013). "In support of this notion, the loss of glioma cell survival upon APPL2 knockdown can be rescued either by an excess of netrin‐1, the prosurvival ligand of UNC5B or by simultaneous silencing of HRK." (PMID 22989406, 2013). "Studies of cell survival in glioma show that netrin acts as a pro-survival ligand for UNC5B in glioma as well, while also promoting invasion and angiogenesis of GBM cells by activating RhoA, cathepsin B, cAMP response element binding protein, and Notch signaling." (PMID 34359681, 2021). "We show that modulation of APPL2 level in glioma cells changes the expression of genes responsible for cell death induction, HRK and UNC5B, suggesting one possible molecular mechanism by which APPL2 may enhance tumor cell growth and apoptosis resistance." (PMID 22989406, 2013).
colitis (3 papers, 2012 to 2014). Inflammation of the colon. "To determine the role of UNC5B in DSS-induced colitis, we used mouse with one allele of UNC5B deleted." (PMID 24720832, 2014). "DSS colitis was performed in mice with partial genetic UNC5B deficiency (UNC5B+/− mice) or wild-type mice to examine the role of endogenous UNC5B." (PMID 24720832, 2014). "However, UNC5B−/+ mice developed much severe colitis as seen by significant loss of bw, increase in colon weight and reduction in colon length." (PMID 24720832, 2014). "Partial deletion of UNC5B exacerbated DSS colitis suggesting protective function of UNC5B against colitis." (PMID 24720832, 2014). "In the present study, we investigated the hypothesis that UNC5B receptor may be a critical mediator of cell survival in response to injury using UNC5B heterozygous knockout mice in a model of DSS colitis." (PMID 24720832, 2014). "As such, we provide evidence that UNC5B act as survival receptor during DSS-induced colitis and might serve as potential therapeutic target to prevent colon injury in the future." (PMID 24720832, 2014).
colon cancer (3 papers, 2020 to 2023). "Increased expression levels of NTN1 and its receptor NEO1 in the visceral adipose tissue from patients with obesity and colon cancer together with elevated DCC and UNC5B mRNA levels in patients with colon cancer were found." (PMID 36831381, 2023). "Like NOVA2, UNC5B-Δ8 is aberrantly expressed in colon cancer vasculature where its expression correlates with tumor angiogenesis and poor patient outcome." (PMID 34381052, 2021). "We also found that high NOVA2 and UNC5B-Δ8 expression levels correlated with short overall survival in colon cancer patients." (PMID 34381052, 2021). "Moreover, UNC5B-Δ8 is aberrantly expressed by ECs of human colon cancer vasculature, correlating with tumor angiogenesis and poor patient survival." (PMID 34381052, 2021). "To evaluate the role of O-GlcNAcylation in the epigenetic downregulation of the UNC5 family, we first examined the expression of UNC5A, UNC5B, UNC5C and UNC5D transcripts in the human colon cancer cell line HCT116." (PMID 33126652, 2020).
diabetes (3 papers, 2014 to 2019). "Consistent with downregulation of plasma netrin-1, both netrin-1 and UNC5B mRNA were found to be significantly downregulated in diabetic kidney as compared to control." (PMID 24991088, 2014). "This review will focus on one such counteractive anti-inflammatory pathway netrin-1 and its receptor UNC5B in the regulation of inflammation during acute (ischemic, drug induced) and chronic (diabetes) kidney injury." (PMID 24991088, 2014).
ischemia (3 papers, 2012 to 2019). A hypoperfusion of the BLOOD through an organ or tissue caused by a PATHOLOGIC CONSTRICTION or obstruction of its BLOOD VESSELS, or an absence of BLOOD CIRCULATION. "To gain further insight into the potential role of UNC5B as a therapeutic target we administered 2.5 μg antibody at time point of ischemia and following reperfusion in 100 μl PBS against UNC5B per mouse (WT+UNC5B-AB) 30 minutes prior to ischemia." (PMID 23936025, 2013). "During ischemia–reinventing blood flow, netrin-1 enzyme is significantly down-regulated, UNC-5B mRNA expression is increased, and the DCC receptor is not changed significantly." (PMID 31663032, 2019).
melanoma (3 papers, 2022 to 2025). A malignant, usually aggressive tumor composed of atypical, neoplastic melanocytes. "NTN1 knockdown induced increased expression of UNC5B and significantly weakened cell migration and invasion abilities in melanoma." (PMID 38546656, 2024). "By the comprehensive analysis of tumor–immune system interactions, we found that the difference in UNC5B expression was significant in urothelial carcinoma and melanoma immunotherapy, and the difference in NTN1 expression was also significant in melanoma immunotherapy." (PMID 41407823, 2025). "Because Flrt2 acts primarily as a repulsive ligand for the Unc5b receptor, we injected endothelial cell–specific Unc5b-knockout mice (Cdh5-BAC-CreERT2Unc5bfl/fl; referred to hereafter as Unc5biΔEC mice) with B16 melanoma cells." (PMID 35104247, 2022).
Obesity (3 papers, 2019 to 2023). Accumulation of substantial excess body fat. "Subsequently, we compared the impact of the adipocyte-derived secretome from patients with obesity and NTN-1 on the expression levels of NEO1, DCC, and UNC5B in two human colorectal cell lines, Caco-2 and HT-29." (PMID 36831381, 2023).
osteosarcoma (3 papers, 2022 to 2024). A usually aggressive malignant bone-forming mesenchymal neoplasm, predominantly affecting adolescents and young adults. "Our findings revealed that UNC5B expression was associated with patient prognosis and that UNC5B mRNA levels were elevated in ferroptotic osteosarcoma cells." (PMID 36330451, 2022). "After that, FAGs in the turquoise module were utilized to construct a prognostic multigene (COL5A2, HOXB4, and UNC5B) signature for risk stratification in osteosarcoma." (PMID 36330451, 2022). "A total of three FAGs, COL5A2, HOXB4, and UNC5B, were ultimately used to construct a prognostic signature for osteosarcoma." (PMID 36330451, 2022). "Given UNC5B’s dual involvement in malignancies, it is worth investigating its role in osteosarcoma, particularly its influence on the ferroptotic process." (PMID 36330451, 2022). "We identified three FAGs (COL5A2, HOXB4, and UNC5B) as potential therapeutic targets and important regulators of ferroptosis in osteosarcoma." (PMID 36330451, 2022). "We also identified COL5A2, HOXB4, and UNC5B as potential therapeutic targets and important regulators of ferroptosis in osteosarcoma." (PMID 36330451, 2022). "Besides, expression of UNC5B, CAM1, PTH1R, and FCGR3A was significantly associated with survival of patients with osteosarcoma." (PMID 37457661, 2023). "In TCGA cohort, Kaplan–Meier survival analysis revealed that increased COL5A2 and UNC5B expression indicated a worse prognosis in patients with osteosarcoma, but HOXB4 expression was not linked with patients’ clinical fate." (PMID 36330451, 2022). "Moreover, UNC5B is a crucial regulator of ferroptosis in osteosarcoma cells." (PMID 38575966, 2024). "More interestingly, ALPL, UNC5B, and CADM1 were also highly and specifically expressed in osteosarcoma compared with most normal human organs based on the TCGA and GTEx databases." (PMID 37457661, 2023). "Consistent with the RNA-seq data, the mRNA levels of COL5A2 and HOXB4 were lower and UNC5B mRNA levels were higher in RSL3-treated cells than in control cells, indicating the probable roles of the three FAGs in the ferroptotic processes of osteosarcoma cells." (PMID 36330451, 2022). "In osteosarcoma U2OS cells, doxycycline-induced expression of polyomavirus small T antigen (PyST) resulted in mitotic arrest and extensive cell death, accomplished by increased mRNA levels of UNC5B, showing the apoptotic activity of UNC5B in osteosarcoma." (PMID 36330451, 2022).